SPOCK1 (SPARC (osteonectin), cwcv and kazal like domains proteoglycan 1)
Diseases named in the same sentence as SPOCK1 in open-access papers (continued):
Sharing a sentence is not in itself a finding about the gene and the disease.
tumor (continued). "Consistently, SPOCK1 was significantly more highly expressed in the tumor region compared to the normal group." (PMID 38087364, 2023). "The results from CIBERSORT and TIMER revealed that SPOCK1 and POSTN were associated with tumor-infiltrating immune cells, especially macrophages and neutrophils." (PMID 36611136, 2023). "In tumor tissues, the tumor cells mainly exhibited moderate or strong diffuse granular cytoplasmic SPOCK1 staining." (PMID 37046698, 2023). "The effects of SPOCK1 expression on tumor growth were further monitored weekly by bioluminescence imaging." (PMID 36766694, 2023). "Knockdown and overexpression of SPOCK1 in ccRCC cells led to decreased and increased cell clonogenic and migratory/invasive abilities in vitro as well as lower and higher tumor growth and invasion in vivo, respectively." (PMID 36766694, 2023). "In all samples, the majority of tumor cells still expressed SPOCK1, but the staining intensity was milder, compared to the smooth muscle cells of vessels." (PMID 37046698, 2023). "We next evaluated the function of SPOCK1 in modulating cell migration and invasion, two fundamental steps of tumor metastasis, in these ccRCC cell lines." (PMID 36766694, 2023). "In terms of immune infiltration, SPOCK1 exhibited a positive correlation with the infiltration of cancer-associated fibroblasts (CAF), myeloid-derived suppressor cells (MDSCs), tumor-associated macrophages (TAMs), and regulatory T cells (Tregs)." (PMID 38087364, 2023). "Significantly higher SPOCK1 transcripts were observed in ccRCC patients with an advanced stage (stages 3 and 4), larger tumor (T3 and T4), and lymph node and distal metastases (N1 and M1)." (PMID 36766694, 2023). "In the validation phase, SPOCK1 and POSTN have highly expressed in tumor cells and CAF for CRC, and the expressions associated with CAF have a poor prognosis and late clinical stage of CRC." (PMID 36611136, 2023). "From in vivo photon emission detection, we found that SPOCK1 overexpression promoted and SPOCK1-KD attenuated tumor growth compared to the control group." (PMID 36766694, 2023). "Here, higher SPOCK1 transcript and protein levels were observed in ccRCC tissues compared to normal tissues and correlated with advanced clinical stages, larger tumor sizes, and lymph node and distal metastases." (PMID 36766694, 2023). "The results demonstrated a significant decrease in the promoter methylation levels of SPOCK1 in tumor patients compared to the normal group." (PMID 38087364, 2023). "Our results showed that SPOCK1 expression was enriched in ccRCC tissues, but was very low in normal kidney and benign tumor tissues." (PMID 36766694, 2023). "In this study, a series of in vitro and in vivo assays showed that cancer cell proliferative and metastatic capabilities were significantly inhibited by KD and enhanced by the overexpression of SPOCK1, suggesting its role in tumor growth and motility of ccRCC." (PMID 36766694, 2023). "The regulation of tumor cell invasion and metastasis by SPOCK1 is an important factor contributing to poor prognosis in LUAD patients." (PMID 38087364, 2023). "Human Protein Atlas provides several examples of cancer tissues expressing ample amounts of SPOCK1 in the tumor cells." (PMID 35186754, 2022). "There is extensive information about the role of SPOCK1 in the tumour extracellular matrix (ECM) dynamic homoeostasis process, which activates many molecular signalling pathways (such as EMT process, Wnt/β-catenin, PI3K/Akt and mTOR/S6K signalling pathways)." (PMID 35046388, 2022). "We studied if the presence or overexpression of syndecan-1 the major transmembrane heparan sulfate proteoglycan of the liver can interfere with the tumor-induced upregulation of SPOCK1." (PMID 35186754, 2022). "Mechanically, miR-940 serves as a tumor suppressor via targeting genes associated with tumor progression including H1HR and SPOCK1 in HCC." (PMID 35140333, 2022).
tumor (continued). "SPOCK1, however, showed three different patterns including apical (staining at the apical cell membrane of tumor cells), cytoplasmic and nuclear staining." (PMID 35221802, 2022). "Although the regulators of SPOCK1 vary in different cancer types, its tumor-promoting effects are predominantly through PI3K/Akt and Wnt/beta-catenin pathways." (PMID 35221802, 2022). "Control cells were compared with SPOCK1 siRNA silenced and SPOCK1 expression vector-transfected tumor cells following BrdU uptake for 30 min." (PMID 35186754, 2022). "The SPI was calculated based the prognostic model, including BOC, GRIA3, MME, SPOCK1, and KNSTRN, which were associated with stemness, TNM stage, prognosis, and tumor microenvironment (TME)." (PMID 35360859, 2022). "The results showed that GPI, IL22RA1, CCT6A, and SPOCK1 expression in the tumor tissues (T) was markedly higher than in the control tissues (N) (n=40, P<0.05)." (PMID 35433415, 2022). "Migration and invasion of HLE and Huh7 tumor cells in control and SPOCK1 siRNA silenced samples showed that siRNA inhibited both migration and invasion of HLE cells." (PMID 35186754, 2022). "In the next step, an experimental hepatocarcinogenesis model was designed, by utilizing the genotoxic diethylnitrosamine as a proxy carcinogen to follow the changes of SPOCK1 during the process of tumor development." (PMID 35186754, 2022). "It was found that LOXL2, PLOD2, MMP14 and SPOCK1 were upregulated in tumor samples, whereas DCN was downregulated in tumor specimens." (PMID 36186418, 2022). "Overexpression of miR-139-5p suppressed HCC cell viability and invasion by targeting SPOCK1, promoted apoptosis, and inhibited tumor growth." (PMID 34522182, 2021). "The tumor volumes formed by cells with high SPOCK1 expression were significantly greater than those from cells with low SPOCK1 expression." (PMID 33293473, 2020). "IHC analysis showed that SPOCK1 was related to tumor histological differentiation and LN metastasis." (PMID 33293473, 2020). "Protein–protein network analysis showed that SPOCK1 is a protein secreted by adjacent mucosa and interacts with a receptor in tumour." (PMID 32599859, 2020). "SPOCK1 knock-down strongly reduces tumor growth and metastasis in an in vivo model of breast cancer." (PMID 33330449, 2020). "In summary, this study contributed to illuminating the molecular mechanism by which SPOCK1 overexpression in human BC potentiated tumor progression." (PMID 33293473, 2020). "In disagreement with our experimental data, SLC6A3 expression analysis revealed higher levels in tumours and SPOCK1 presented similar expression levels in both tissues." (PMID 32599859, 2020). "Of note, some of our tumour samples have shown higher SPOCK1 expression than their matched-normal sample, indicating that its expression is highly variable." (PMID 32599859, 2020). "With a more advanced tumor value, the ratio of high SPOCK1 expression became more dominant, which supports the result of an advanced cancer stage accompanying high SPOCK1 expression." (PMID 31284511, 2019). "In clinical, SPOCK1 levels were higher in tumor tissues compared to non-tumor tissues, which was also significantly correlated with shorter disease-free survival in PCa patients." (PMID 31182131, 2019). "Statistically significant differences for SPOCK1 expression were noted in the pathological disease stage and the tumor (T) value (p = 0.018 and 0.014, respectively)." (PMID 31284511, 2019). "Our findings demonstrated the importance of increased SPOCK1 expression as a common event, a prognostic indicator of PCa tumorigenesis, and a potential link to tumor metastasis." (PMID 31182131, 2019). "Overexpression of SPOCK1 in PCa xenografts resulted in significant promotion of tumor progression and relieved the anticancer activities induced by API, whereas knockdown of SPOCK1 had opposite effects." (PMID 31182131, 2019).
tumor (continued). "The protein expression of SPOCK1 in tumour tissues confirmed the down‐regulation of SPOCK1 resulted from miR‐139‐5p, miR‐940 and miR‐193a‐5p." (PMID 30710422, 2019). "The SPOCK1 expression in these tumour tissues showed that overexpression of miRNAs significantly decreased the expression of SPOCK1." (PMID 30710422, 2019). "Sparc/osteonectin, cwcv, and kazal-like domains proteoglycan 1 (SPOCK1) is a crucial modulator of tumor growth and metastasis in cancers." (PMID 31182131, 2019). "Using cocultures of human tumor cells and mouse fibroblasts to model the stroma, followed by species‐specific RNA‐Seq analysis, we have previously identified mouse Spock1 as a stromal target gene of tumor cell‐derived SHH." (PMID 28486750, 2017). "The organotypic coculture data together with the analyses of collagen composition show that SPOCK1 in stromal cells functions to modify the collagen matrix and thereby facilitates the invasive growth of tumor cells." (PMID 28486750, 2017). "An important question left unexplored in this study is the correlation of stromal SPOCK1 expression with important tumor‐promoting stromal features in patient tumor material." (PMID 28486750, 2017). "Spock1 levels were almost undetectable in monoculture of these MEFs, and coculturing MEFs with tumor cells was necessary to induce expression." (PMID 28486750, 2017). "To further delineate the source of SPOCK1 in human tumors and confirm its expression to be confined to tumor stroma, we performed extensive analysis on publically available gene expression data." (PMID 28486750, 2017). "In bulk tumor‐derived expression data, we found a very strong correlation of SPOCK1 expression with markers of activated stroma: secreted protein acidic and cysteine rich (SPARC), α‐smooth muscle actin (αSMA/ACTA2), and fibroblast activation protein." (PMID 28486750, 2017). "Coculture and ligand stimulation experiments revealed that SPOCK1 is expressed in response to tumor cell‐derived transforming growth factor‐beta." (PMID 28486750, 2017). "In this study, we have addressed tumor‐promoting stromal factors and identified SPOCK1 as a mediator of extracellular matrix remodeling and invasive tumor growth." (PMID 28486750, 2017). "The thickness of this layer was much reduced in cocultures with shSpock1 MEFs, suggesting a role for stromal SPOCK1 in facilitating tumor growth." (PMID 28486750, 2017). "Functional assessment in cocultures demonstrated that SPOCK1 strongly affects the composition of the extracellular collagen matrix and by doing so, enables invasive tumor cell growth in PDAC." (PMID 28486750, 2017). "SPOCK1 acted as a potential prognostic factor for pregression and took part in tumor proliferation and metastasis through the ERK and AKT signaling pathways." (PMID 29340021, 2017). "We have shown that SPOCK1 affects tumor cells by acting on the extracellular collagen, thereby facilitating tumor cell expansion." (PMID 28486750, 2017). "These smaller colonies were seemingly incongruent with the unchanged number of tumor cells as counted by FACS, and implied that more tumor cells occupied a smaller surface area in these Spock1‐knockdown cocultures." (PMID 28486750, 2017). "Instead, we find that in PDAC, SPOCK1 is confined to the stromal compartment but indirectly affects the proliferation and invasion of tumor cells." (PMID 28486750, 2017). "In all cocultures, an induction of SPOCK1 expression in stellate cells was observed, confirming it to be a consistent target of tumor cell‐derived signals in stromal cells." (PMID 28486750, 2017). "SPOCK1 belongs to the Ca2+-binding proteoglycan family which includes SPARC, a well-studied tumor-associated component involved in regulating adhesion, matrix cellular interactions, and cell growth." (PMID 28103946, 2017). "In this study, we analyzed the involvement of a novel proteoglycan, Sparc/osteonectin, cwcv, and kazal-like domains proteoglycan 1 (SPOCK1), in the tumor progression and prognosis of human GBC." (PMID 25623055, 2015).
tumor (continued). "Our results suggest that inactivation of PI3K/Akt signaling is responsible for SPOCK1 shRNA-mediated suppression of tumor cell proliferation, migration, invasion, and EMT." (PMID 25623055, 2015). "A series of in vitro and in vivo assays showed that cancer cell growth, DNA replication and the colony formation capability were significantly decreased by inhibition of SPOCK1, suggesting its role in cancer cell proliferation and tumor growth." (PMID 25623055, 2015). "In contrast, SPOCK1 is primarily an extracellular matrix (ECM)-associated protein that predominantly exerts functional roles such as promoting cell invasion, metastasis, and regulating the tumor microenvironment." (PMID 40837013, 2025). "Inhibit SPOCK1 expression reducing proliferation and invasion of tumor cells." (PMID 41465470, 2025). "This suggests that SPOCK1 could potentially contribute to an immunosuppressive tumor microenvironment by aiding the expression of PD-1/PD-L1." (PMID 40001977, 2025). "This bidirectional correlation suggests that SPOCK1 may have context-dependent immunomodulatory roles across different tumor immune landscapes." (PMID 40837013, 2025). "However, in the tumor microenvironment, SPOCK1 appears to be co-opted to promote tumor cell proliferation, migration, and immune evasion." (PMID 40837013, 2025). "Finally, FAP was associated with ECM and adhesion genes (FN1, COL5A1, SPOCK1, CDH13) and regulators of migration (NREP, SEMA5A), consolidating its central role in matrix deposition and tumor invasion, as previously shown." (PMID 41198614, 2025). "Furthermore, CAFs in tumor samples showed significantly higher SPOCK1 expression than those in normal samples." (PMID 40837013, 2025). "Our study underscores the translational relevance of SPOCK1 as a candidate therapeutic target and highlights the unique value of integrating single-cell and spatial transcriptomic approaches to unravel the complexity of tumor–stroma–immune interactions." (PMID 40837013, 2025). "We observed that SPOCK1 expression (hazard ratio (HR), 1.630; p = 0.002), age (HR, 1.771; p < 0.001), clinical stage (HR, 3.833; p < 0.001), tumor size (HR, 3.151; p < 0.001), and distal metastasis (HR, 2.143; p < 0.001) were all shown to have adverse impacts on OS." (PMID 36766694, 2023). "For example, SPOCK1 (which encodes SPARC or osteonectin) is involved in cell-cell and cell-matrix interactions and has been associated with induction of EMT and invasion in multiple tumor types." (PMID 36881486, 2023). "In tumors, the tumor cells showed diffuse granular cytoplasmic SPOCK1 staining." (PMID 37046698, 2023). "In summary, the increased presence of these immune suppressive components within the tumor microenvironment may partially explain the poor prognosis of the high SPOCK1 expression group." (PMID 38087364, 2023). "We propose that, based on our findings on tumor tissue materials and serum samples, SPOCK1 may be a candidate for detecting the efficacy of chemotherapy, as its level decreases in samples from patients who have received chemotherapy." (PMID 37046698, 2023). "A higher number of Ki67 positive tumor cells were observed in tumors producing abundant SPOCK1." (PMID 37046698, 2023). "In one of the tumors, we saw heterogeneous SPOCK1 expression, where some tumor cell groups showed strong expression, while in other areas, milder expression could be seen." (PMID 37046698, 2023). "Similarly to other cancers, tumor tissues had higher SPOCK1 levels than non-tumor tissues, and PaC patients with a high SPOCK1 expression had a worse median overall and disease-free survival." (PMID 37046698, 2023). "Furthermore, the heatmap including SPOCK1 expression and tumor stage exhibited good predictive performance for prognosis." (PMID 38087364, 2023). "SPOCK1 was reported to connect with tumor immune infiltrates and may be a useful prognostic biomarker and act a carcinogenic gene in CRC." (PMID 37779184, 2023).
tumor (continued). "Furthermore, DFS was also adversely affected by high SPOCK1 expression (HR, 3.610; p = 0.028), tumor size (HR, 3.401; p = 0.019), and an advanced stage (HR, 3.440; p = 0.018)." (PMID 36766694, 2023). "In addition, SPOCK1 has been shown to be involved in tumor metabolism such as glucose consumption and lactic secretion and to promote the Warburg effect." (PMID 37046698, 2023). "However, when tumor grade was considered, high SPOCK1 expression in patients with grade 1 and 2 tumors had a much more pronounced effect on survival, increasing the hazard ratio to 1.78 (n = 260, FDR = 1%)." (PMID 37046698, 2023). "We next examined the in vivo effects of SPOCK1 expression on ccRCC tumor progression." (PMID 36766694, 2023). "In NSCLC, SPOCK1 expression is significantly higher in tumor than in non-tumor tissues." (PMID 37511221, 2023). "Moreover, the results showed that the expression levels of LOXL2, PLOD2, MMP14 and SPOCK1 was higher whereas that of DCN was lower in tumor tissues compared with normal tissues." (PMID 36186418, 2022). "In addition, three tumor-specific genes, namely, SPOCK1, PTGIS and NDUFA4L2, were verified using IHC-P in type 2 pRCC tissues (–D) and compared with the negative controls in normal kidney tissues (–C)." (PMID 34722263, 2021). "Thus, the results identified some new tumor-specific markers and verified SPOCK1, PTGIS, REG1A, CP and SPAG4 in different types of RCC." (PMID 34722263, 2021). "Additionally, SPOCK1 has been regarded as a candidate oncogene and have been verified to be closely related to the tumorigenesis, tumor progression, adhesion and metastasis of various tumors." (PMID 33293473, 2020). "The role of SPOCK1 in PCa shows that it acts as a critical mediator in tumor growth and metastasis." (PMID 31284511, 2019). "Therefore, the results indicated that miR‐139‐5p, miR‐940 and miR‐193a‐5p inhibited tumour growth in vivo through down‐regulating the expression of SPOCK1." (PMID 30710422, 2019). "Thus, we propose that when FOXI3 in tumor cells modulate the secretion of other bone factors including SPOCK1, Dlx, MAF, PthrP, HAS2, SVEP1, TGFβ3, and FGF which further primes the microenvironment, creates a crosstalk to help tumors grow in the bone." (PMID 30018953, 2018). "It is possible that the longer culturing made possible by organotypic cocultures is responsible for this, but it is also possible that the tumor–stroma interaction needs a three‐dimensional configuration for the growth‐promoting effects of SPOCK1 to become apparent." (PMID 28486750, 2017). "This analysis revealed that indeed, control and shSpock1 cocultures exerted differential effects on the collagen matrix, suggesting that Spock1 could alleviate the constraints exerted on tumor cells by acting on the extracellular matrix." (PMID 28486750, 2017). "The identification of SPOCK1 as a stromal target for tumor cell‐derived ligands and its prognostic power raise the question whether it has a functional role in driving tumor biology." (PMID 28486750, 2017). "Moreover, SPOCK1 ablation severely decreased orthotopic tumor growth and reduced bone metastatic osteolytic tumors." (PMID 28103946, 2017). "This indirect, extracellular matrix‐mediated effect of SPOCK1 could also explain its correlation with poor prognosis in other (non‐PDAC) tumor types." (PMID 28486750, 2017). "SPOCK1 silencing resulted in a significant reduction in tumor growth." (PMID 28103946, 2017). "Further experiments revealed that SPOCK1-enhanced tumor cell survival may be attributable to its anti-apoptotic effect." (PMID 25623055, 2015). "Our data suggest that SPOCK1 promotes tumor invasion and metastasis via inducing EMT." (PMID 25623055, 2015). "Conversely, compared with empty vector-transfected cells, SPOCK1-transfected cells showed increased growth rates (P < 0.01), greater colony forming abilities (P < 0.001), increased DNA replication, larger mean tumor volume (P < 0.05) and higher Ki-67 index." (PMID 25623055, 2015).